HPSE (heparanase)
Diseases named in the same sentence as HPSE in open-access papers (continued):
Sharing a sentence is not in itself a finding about the gene and the disease.
tumor (continued). "The mRNA level of HPSE in 83 (83/112 = 74.1%) cases was reduced in tumor tissues compared with non-tumor liver tissues." (PMID 22952874, 2012). "Compound 4 inhibits heparanase, but does not inhibit P-selectin, so it is an anti-metastatic drug only for some species of tumours." (PMID 22902885, 2012). "Untreated tumor sections showed no staining with 3G10, whereas tumor sections treated with heparanase displayed substantial positivity for the 3G10 epitope predominantly localized to vessel-like structures that closely resembled the αHS staining pattern." (PMID 23152853, 2012). "Heparanase also liberates and activates heparin-binding growth factors bFGF and VEGF from the ECM, which may act in a paracrine manner with the tumour." (PMID 22720169, 2012). "Heparanase is an endo-β-glucuronidase that degrades heparan sulfate (HS), a major constituent of the extracellular matrix (ECM) and basement membrane, and this enzyme plays a role in tumor metastasis and angiogenesis." (PMID 23300607, 2012). "Here, we examined the effect of PG545 on heparanase protein expression using samples from primary tumor tissue (taken at mastectomy) and lung tissue during the survival studies and found that PG545 significantly inhibited the expression of heparanase in both tumor tissue and lung tissue." (PMID 23300607, 2012). "HPSE mRNA level was notably reduced in 74.1% (83/112) of tumor tissues compared with non-tumor liver tissues, which was significantly associated with DNA copy number loss, increased tumor size, and post-operative metastasis." (PMID 22952874, 2012). "T5 splice variant is endowed with pro-tumorigenic properties, enhancing cell proliferation, anchorage independent growth and tumor xenograft development despite lack of heparan sulfate-degrading activity typical of heparanase." (PMID 23251556, 2012). "The hemostatic function of heparanase, executed by inducing TF expression and releasing TFPI from the endothelial cell surface, provides a mechanism by which heparanase contributes to tumor complication, in addition to its established proangiogenic and prometastatic activities." (PMID 23908827, 2012). "Heparanase is known to promote progression in a number of cancers and its presence may be a major determinant on whether SDC-1 plays a tumor-promoting or tumor inhibitory role." (PMID 21655218, 2011). "Given the well documented role of heparanase in tumor metastasis and angiogenesis, it is plausible that insulin, with or without glucose, stimulates secretion of active heparanase by tumor cells, thus accelerating tumor progression." (PMID 21364956, 2011). "A total of 56 molecules are annotated as affecting neoplasia and eight of these are dysregulated over 1.5 fold in Ad12-TC compared to Ad5-TC: down-regulation of ATM, CD19, CD3G, GADD45B, HPSE, TFAP2A and TFPI was observed, whereas levels of EGFR were found to be up-regulated." (PMID 19200380, 2009). "Heparanase cleaves HS residues, participates in ECM degradation, and thereby may facilitate tumor cell invasion." (PMID 18647407, 2008). "Non-enzymatic activities of heparanase include enhanced adhesion of tumor-derived cells and primary T-cells." (PMID 18545691, 2008). "Increased expression of heparanase mRNA and protein has been reported in a variety of metastatic cell lines and human tumor tissues, whereas adjacent normal-looking tissue does not exhibit detectable levels of heparanase." (PMID 18647407, 2008). "In contrast, heparanase showed high, moderate, or no expression in 17, 22, and 11 tumour specimens, respectively." (PMID 11953884, 2002). "Postoperative survival correlates inversely with heparanase expression of the tumour reflected by a median survival of 34 and 17 month for heparanase negative and positive tumours, respectively." (PMID 11953884, 2002). "Mean postoperative survival was 34 months and 17 month in heparanase negative and positive tumours (R0 resection), respectively." (PMID 11953884, 2002).
tumor (continued). "In addition, considering previous reports showing that KD of BPTF attenuates HPSE expression, an enzyme critical for the cleavage of NCR ligands on the surface of tumor cells, we aimed to investigate whether this regulatory effect exists in HCC." (PMID 39935175, 2025). "In the described studies, genetic constructs effectively reduced heparanase enzyme expression, resulting in reduced tumor invasiveness and suppression of angiogenesis and metastasis, but approaches based on genetic suppression of heparanase have not been widely used in clinical trials." (PMID 39594665, 2024). "Our earlier studies showed that heparanase up-regulated the expression of TF and interacted with the tissue factor pathway inhibitor (TFPI) on the cell surface membrane of endothelial and tumor cells, resulting in TFPI dissociation and increased cell surface coagulation activity." (PMID 39766213, 2024). "Conversely, nuclear heparanase binds nonspecifically to DNA and competes for binding with nuclear factor‐κB (NF‐κB), thus preventing transcription of NF‐κB target genes and acting as a tumor suppressor." (PMID 37547889, 2023). "RELMβ is positively correlated with tumor differentiation in gastric cancer and negatively associated with lymph node metastasis, tumor infiltration, and heparanase expression, independent of age, gender, tumor location and size, tumor-node metastasis stages, and Ki-67 expression." (PMID 36691020, 2023). "However, our findings indicate that lung metastasis in tumour-bearing female MMTV-PyMT mice remained unaffected by the lack of HPSE expression in the host tissue." (PMID 37297024, 2023). "Moreover, we identified possible communications mediated by heparanase and galectin-1 which could regulate ECM remodeling and tumor immune microenvironment (TIME) reshaping." (PMID 36189263, 2022). "In addition, tumor tissue showed an increase in heparanase, MMP9, PPARγ, and IFNγ, while non-tumor adjacent tissue showed an increase in E-cadherin and COX2 and a decrease in IL-4R." (PMID 36139645, 2022). "Additionally, according to univariate logistic regression, a tumour diameter larger than 2 cm, and the lack of ER and PgR expression were strong influences on high pre-treatment heparanase in IBrC patients." (PMID 34070058, 2021). "Several lines of evidence suggest that unlike heparanase, Hpa2 functions to attenuate tumor growth." (PMID 33959505, 2021). "Two anti-heparanase antibodies (multiple antigenic peptides MAP1-2) can effectively prevent the heparanase activity of hepatic cancer cells (HCCLM6), thereby affecting their invasive capability and indicating their pivotal role in HCC tumor growth and metastasis." (PMID 33411145, 2021). "Finally, a higher post-treatment concentration of heparanase was found in patients with a triple-negative tumour compared to patients with a luminal B HER2 negative type of IBrC." (PMID 34070058, 2021). "The risk of disease recurrence following chemotherapy for patients with increased heparanase expression was significantly greater than for patients with low heparanase expression, regardless of tumor molecular subtype, suggesting that heparanase expression is predictive for chemotherapy resistance." (PMID 34050190, 2021). "Conversely, nuclear heparanase has also been shown to bind non-specifically to DNA and compete for binding with NF-κB, thus preventing transcription of many NF-κB target genes and acting as a tumor suppressor." (PMID 34681753, 2021). "While heparanase upregulation by tumor cells is well documented, not enough attention has been given to the protumorigenic function of heparanase expressed by non-tumor cells residing in the tumor microenvironment." (PMID 31963505, 2020). "Moreover, the finding that exogenous heparanase can enhance nuclear acetyltransferase activity indicates that tumor cells do not necessarily have to be producing heparanase for it to regulate gene expression." (PMID 32899927, 2020).
tumor (continued). "As the complexity of the role of HPSE in cancer continues to unravel, it is now clear that a one-size-fits-all approach may not be ideal in certain tumour settings." (PMID 33256730, 2020). "Thus, the balance between the level of nuclear and non-nuclear heparanase and syndecan-1 shedding potentially provides a mechanism for fine-tuning the expression of multiple genes that regulate tumor behavior." (PMID 32899927, 2020). "There is no clear evidence for the direct involvement of HPSE in tumour necrosis." (PMID 33256730, 2020). "Interestingly, peptides from TFPI-2 that inhibited the procoagulant activity of heparanase, but not the catalytic activity, also reduced tumor growth and vascularisation in murine tumor models." (PMID 31850210, 2019). "An issue that remains unresolved is to what extent the cargo contained in these exosomes is responsible for the effects attributed to heparanase in sustaining tumor growth, tumor cell invasion, and the augmentation of angiogenesis, rather than heparanase itself." (PMID 31850210, 2019). "Additionally, immunostaining of the mouse tumor tissues with heparanase antibody revealed that Panc02 carcinoma cells, rather than host-derived stromal cells, represent the main source of the enzyme in tumors growing in hyperglycemic mice." (PMID 31921662, 2019). "This study also showed that heparanase negative macrophages, in contrast to WT-macrophages, could not invade tumor tissue in response to CXCL2 and did not attenuate tumor growth." (PMID 31850210, 2019). "However, like heparanase, it has a role in cancer, but generally in tumor suppression, not tumor promotion as is seen with the catalytic protein." (PMID 31850210, 2019). "Loss of nuclear syndecan-1 was shown to be induced by elevated levels of heparanase, which resulted in a significant increase in histone acetylase activity, leading, in turn, to stimulation of the transcription of genes (i.e., VEGF and MMP-9) that drive aggressive tumor behavior." (PMID 30413079, 2018). "This may be the reason that HPSE overexpression, which functionally induced trophoblasts to approach tumor cells, did not affect tube formation in HTR8/SVneo cells." (PMID 29849826, 2018). "Heparanase immuno-reactivity was noted in the lung tumor and lymph-node metastasis but not in the normal lung tissue adjacent to the primary tumor." (PMID 29721203, 2018). "Interestingly, we found that heparanase expression in the metastatic lesion does not always reflect its expression in the primary tumor." (PMID 29464068, 2018). "Some researchers have also demonstrated that the release of specific enzymes by T cells, known as heparanase (HPSE), which can help immunocytes pass through physical barriers with degradation of extracellular matrix (ECM) that possesses an ability to prevent the T cells homing to tumor site." (PMID 28049484, 2017). "While heparanase may have important roles in supporting tumour angiogenesis, it is important to recognise that it is not the only mechanism." (PMID 27408707, 2016). "Over-expression of Smad4 rescued the NB cells from LEF1-facilitated growth, invasion and angiogenesis, suggesting that Smad4 may exert its tumor suppressive functions, at least in part, through interacting and repressing the LEF1 activity in regulation of HPSE expression in NB." (PMID 27595937, 2016). "Heparanase (HPSE), an enzyme that cleaves the heparan sulfate chains of proteoglycans in the tumor microenvironment, has been shown by us and others to promote tumor growth, angiogenesis and correlate with bone metastasis of a variety of cancer cells, including MM." (PMID 26849235, 2016). "Additionally, heparanase, an enzyme involved in cleavage and remodeling heparin sulfate proteoglycans in the ECM, accumulates at the HNSCC invasive front, and is a marker of poor prognosis for lymph node metastasis and tumor recurrence." (PMID 25734659, 2015).
tumor (continued). "However, previous works also indicated that not all tumor cells expressed heparanase, which indicate that there are different regulatory mechanisms of heparanase expression among tumors." (PMID 24632672, 2014). "Heparanase was shown to up-regulate tissue factor (TF) expression and interact with tissue factor pathway inhibitor (TFPI) on the cell surface, leading to dissociation of TFPI from the cell membrane of endothelial and tumor cells, resulting in increased cell surface coagulation activity." (PMID 23908827, 2012). "Regardless of the mode of action, it appears that heparanase may function as a master regulator of protease expression and activity within tissues and the tumor microenvironment during the course of tissue morphogenesis and tumor progression." (PMID 19360105, 2009). "Heparanase cleavage of HS in the ECM, particularly in epithelial and sub-endothelial basement membranes, is a critical step in cancer development and progression in correlation with metastatic potential, tumor vascularity and reduced survival of cancer patients." (PMID 19715595, 2009). "Indeed, these data suggest that in certain clinical settings, the use of HPSE inhibitors aimed at inhibiting tumour growth through impaired angiogenesis may not prove to be effective." (PMID 37297024, 2023). "Likewise, SST0001, a 100% N-acetylated and glycol split non-anticoagulant heparin with potent anti-heparanase activity, had proved effective in reducing tumor progression and spread in multiple myeloma patients and in Ewing’s sarcoma model, as well as in other human pediatric sarcoma models." (PMID 35329997, 2022). "The results obtained in tumor tissue could indicate that metastasis-signaling pathways could be initially stimulated in stage II, since our results showed a huge increase in heparanase levels in tumor tissue compared to non-tumor adjacent tissue, especially in stage II." (PMID 36139645, 2022). "However, non-enzymatic functions of HPSE have also been described in tumour mechanisms." (PMID 34677445, 2021). "Moreover, as observed in human tumor cultures, in order to access tumor sites and exert antitumor effects, CAR T cells must be able to degrade heparan sulphate proteoglycans (HSPGs) by releasing specific enzymes, such as heparanase (HPSE) in the TME to reach their target." (PMID 33807867, 2021). "Moreover, HPSE was discovered to mediate TLR activation at the cell membrane, followed by Erk/p38/JNK activation therefore regulating cytokine expression by macrophages, their activation and function in tumorigenesis and cross-talk with the tumor microenvironment." (PMID 31963505, 2020). "However, HPSE expression in the primary tumor does not always reflect metastatic output." (PMID 31963505, 2020). "Interestingly, the effect of both T5 and heparanase in this model was not apparent until 3 weeks post subcutaneous inoculation when the development of tumor xenografts expressing either T5 or heparanase was markedly enhanced compared to controls lacking these proteins." (PMID 31850210, 2019). "This may have been a result of the tumor cells upregulating heparanase in response to stimuli from the tumor microenvironment, which could include soluble factors such as TNF-α and IL-1β, or heparanase may have originated from other cell types within the tumor microenvironment (e.g., macrophages)." (PMID 31110966, 2019). "Thus, heparanase inhibition may not be the only reason for the potent anti-tumor activity of PG545, whereas reduced tumor metastasis is likely to result solely from heparanase inhibition." (PMID 29721203, 2018). "Thus, heparanase, is an endoglucuronidase which cleaves heparan sulfate (HS), resulting in alteration of the structure and function of heparan sulfate proteoglycans (HSPG) as well as tumor-dependent remodeling of both cell surface and the extracellular matrix (ECM)." (PMID 28187461, 2017).
tumor (continued). "Likewise, heparanase over-expression enhanced, while local delivery of anti-heparanase siRNA inhibited the progression of tumor xenografts, implying that heparanase function is not limited to tumor metastasis but is also engaged in accelerated growth of the primary lesion." (PMID 24887057, 2014). "Moreover, PG545 down regulates the expression of heparanase in primary tumor tissue and metastatic lung tissue thereby supporting the notion that targeting this enzyme at least contributes to, if not is directly responsible for, the anti-metastatic properties associated with this agent." (PMID 23300607, 2012). "Thus, heparanase may influence the nuclear localization of syndecan-1 broadly throughout the tumor microenvironment, even within cells lacking heparanase expression." (PMID 19305494, 2009). "Thus, the combined effects of heparanase and HSULF could account for the lack of biologically active HS in tumour cells rather than deficiencies in the biosynthetic enzymes." (PMID 17437011, 2007). "Heparanase, MMP9, vimentin, and VEGF-B protein levels, were studied in both tumor and non-tumor adjacent tissues of all stages from CRC patients." (PMID 36139645, 2022). "Results revealed HPSE expression to be a prognostic factor of BRAF V600E-mutant CRC, independent of gender, age, primary location, tumor stage, and MMR status." (PMID 36130926, 2022). "Regarding that the effect of drug treatment on heparanase expression of MDA-MB-435 cells is not significantly in vitro both at mRNA and protein level, only MCF-7 cells were selected for the tumor formation assay in vivo." (PMID 24632672, 2014). "Our research shows that fucoidan dose not inhibit the expressions of VEGF, bFGF, IL-8, and heparanase in HCC cells and/or tumour tissues." (PMID 23737842, 2013). "Notably, the ability of heparanase to activate PI3K/Akt in a nonenzymatic manner, essentially bypassing PTEN signaling, is evidence of its ability to counter tumor‐suppressive mechanisms." (PMID 37547889, 2023).